FCGR2C (Fc gamma receptor IIc (gene/pseudogene))
Description:
Receptor for the Fc region of complexed immunoglobulins gamma. Low affinity receptor. Involved in a variety of effector and regulatory functions such as phagocytosis of immune complexes and modulation of antibody production by B-cells.
Synonyms: Fc-gamma-RIIc; hFcRII-C; CD32C; FcgammaRIIc
Gene: Protein-coding gene on chromosome 1 (161,581,339 to 161,605,662, forward strand). Ensembl gene ENSG00000244682.
Subcellular location: Cytoplasm (Isoform IIC4); Cell membrane (Isoform IIC3); Cell membrane (Isoform IIC2); Cell membrane (Isoform IIC1)
Subcellular location (Human Protein Atlas): Plasma membrane; Golgi apparatus
Genetic constraint (gnomAD): Missense variants: 179 observed, 263.96 expected, observed/expected ratio (o/e) 0.68, 90% interval 0.6 to 0.77. Synonymous variants: 83 observed, 100.75 expected, observed/expected ratio (o/e) 0.82, 90% interval 0.69 to 0.99.
Homologues: Orthologues: macaque FCGR2A (78% identical), guinea pig Fcgr2b (52% identical), dog FCGR2B (48% identical), mouse Fcgr2b (46% identical), rat Fcgr2b (42% identical), mouse Fcgr3 (38% identical), rat Fcgr2a (37% identical), rat Fcgr2al1 (36% identical), rat Fcgr2a (34% identical). Paralogues in human: FCGR2A (84% identical), FCGR2B (81% identical), FCGR3A (31% identical), FCGR3B (30% identical), FCGR1A (28% identical), FCER1A (26% identical), FCRL5 (25% identical), FCRLB (22% identical), FCRL3 (22% identical), FCRL4 (22% identical), FCRLA (19% identical), PECAM1 (16% identical), and 5 more.
Diseases named in the same sentence as FCGR2C in open-access papers:
FCGR2C is named in the same sentence as 31 diseases in open-access papers, as found by Europe PMC text mining. Sharing a sentence is not in itself a finding about the gene and the disease. The quoted sentences say what the papers report.
autoimmune disease (2 papers, 2017 to 2019). A disorder resulting from loss of function or tissue destruction of an organ or multiple organs, arising from humoral or cellular immune responses of the individual to their own tissue constituents. "Because of the linkage disequilibrium and given these functional data, it is more likely that 2B.4 variant or FCGR2C-ORF confer the increased risk for autoimmune disease than FCGR2A-p.62Trp." (PMID 31632391, 2019). "Regarding childhood autoimmune diseases, classic FCGR2C-ORF confers susceptibility to childhood ITP as well as Kawasaki disease." (PMID 31632391, 2019). "In adult autoimmune diseases, there is an association of classic FCGR2C-ORF with ITP." (PMID 31632391, 2019). "Altogether, classic FCGR2C-ORF may thus predispose to autoimmune disease either by providing attenuated innate immune responses or by enhancing the humoral immune response." (PMID 31632391, 2019). "In the studies of genetic predisposition to develop autoimmune disorders, CNV was proven only for FCGR2C, FCGR3A and FCGR3B, but not for FCGR2A and FCGR2B genes." (PMID 28472129, 2017).
autoimmune disorders (2 papers, 2017 to 2024). "It has also been speculated that unexplained cases of early onset severe autoimmunity may result from homozygous deletion of CNR4 because the FCGR2B‐stop variant would not be detected by NGS techniques as all FCGR2B‐stop reads would be mapped to the FCGR2C gene instead." (PMID 39345014, 2024).
Kawasaki disease (2 papers, 2019 to 2022). A rare inflammatory disease characterized by an acute febrile, systemic, self-limiting, medium-vessel vasculitis primarily affecting children. "In Kawasaki disease for example, the association with the FCGR2C-ORF haplotype becomes evident only when Asians, in whom FCGR2C-ORF is a nearly absent haplotype, are excluded from the cohort." (PMID 35688931, 2022). "Classic FCGR2C-ORF and 2B.4 correlate positively to immunomodulatory treatment with response to intravenous immunoglobulins (IVIg) in childhood ITP and, for 2B.4, in Kawasaki disease." (PMID 31632391, 2019).
melanoma (2 papers, 2021 to 2025). A malignant, usually aggressive tumor composed of atypical, neoplastic melanocytes. "In contrast, our study developed a gene-based prognostic model to predict NK cell activation and melanoma prognosis, identifying CCNB1, PRKACB, FCGR2C, and CCL8 as key prognostic genes." (PMID 40430484, 2025). "In this study, 7 genes (CYTL1, CCL8, FCGR2C, OAS1, HAPLN3, WIPF1, CLIC2) were identified as prognostic signatures for melanoma." (PMID 33428606, 2021).
sarcoidosis (2 papers, 2017 to 2023). Sarcoidosis is a multisystemic disorder of unknown cause characterized by the formation of immune granulomas in involved organs. "Therefore, we have analyzed polymorphism of these genes in our SA patients and revealed that, in contrast to polymorphism of FCGR2B and FCGR3B, polymorphism of FCGR2A, FCGR2C and FCGR3A may contribute to immunocomplexemia present in sarcoidosis." (PMID 28472129, 2017). "Therefore, the increased copy number of FCGR2C gene in Stage IV of sarcoidosis might correspond in a great proportion to the functional 57Q variant of the gene, leading to increased FcγRIIc expression and accelerated activation of monocytes, macrophages, neutrophils, NK cells and B lymphocytes." (PMID 28472129, 2017). "A relevant increase in copy number of FCGR2C and FCGR3B in Stage IV of sarcoidosis vs. other stages and controls was detected, but this observation was based on a limited number of Stage IV patients." (PMID 28472129, 2017). "We have detected only a relevant increase in CN of FCGR2C and FCGR3B in the last Stage IV of sarcoidosis vs. other stages and controls, but this observation was based on a limited number of six patients classified to Stage IV of SA." (PMID 28472129, 2017). "We have found a lack of association between copy number of FCGR2A, FCGR2B, FCGR2C, FCGR3A, FCGR3B genes and risk of development of sarcoidosis in our patients." (PMID 28472129, 2017).
sarcoma (2 papers, 2021 to 2022). A usually aggressive malignant neoplasm of the soft tissue or bone. "One bioinformatic analysis reported that the overexpression of the lncRNAs ADAM6, C5orf58, CXCR2P1, FCGR2C, HCP5, HLA-H, NAPSB, NCF1B, and NCF1C reduced the sensitivity of sarcoma to ICIs." (PMID 36326232, 2022). "The expression of nine ICLs, ADAM6, C5orf58, CXCR2P1, FCGR2C, HCP5, HLA-H, NAPSB, NCF1B and NCF1C, was further investigated in different cancer types, including sarcoma." (PMID 34178688, 2021).
tuberculosis (2 papers, 2019 to 2023). A chronic, recurrent infection caused by the bacterium Mycobacterium tuberculosis. "The minorallele of FCGR2C c.169T>C (p.X57Q), whichpredicts expression of functional FcγRIIc, has been associated with autoimmunediseases, HIV-associated tuberculosis and antibody responses following vaccination." (PMID 30563969, 2019).
B cell lymphomas (1 paper, 2022). "Indeed, patients carrying the allelic variants of FCGR2A, FCGR2C, and FCGR3A which exhibit increased affinity for human IgG demonstrated better responsiveness to anti-tumor antibody therapy in cases of B cell lymphomas, colorectal, renal, and breast cancers." (PMID 35372055, 2022).
co-infection (1 paper, 2013). "In this study we investigated whether CNV of FCGR2C, FCGR3A and FCGR3B as well as the HNA1 allotype of FCGR3B is associated with HIV load, response to highly-active antiretroviral therapy (HAART) and co-infection with TB." (PMID 24250791, 2013). "In this study we investigated whether copy number variation of FCGR2C, FCGR3A and FCGR3B as well as HNA1 allelic variation of FCGR3B is associated with HIV load, response to HAART and co-infection with TB in two African populations." (PMID 24250791, 2013).
cytomegalovirus infection (1 paper, 2025). A herpesvirus infection caused by Cytomegalovirus. "One patient, with a preceding cytomegalovirus infection, was identified with three copies of parts of both FCGR3A and FCGR3B and three copies of the entire FCGR2C and HSPA7 genes, suggestive of a novel CNR (CNR5)." (PMID 40593358, 2025). "In the present study, we identified a unique case of a GBS patient with a preceding cytomegalovirus infection who had three copies of parts of FCGR3A and FCGR3B, along with three copies of the entire FCGR2C and HSPA7 genes." (PMID 40593358, 2025).
malaria (1 paper, 2020). Malaria is a serious and sometimes fatal disease caused by a parasite that commonly infects a certain type of mosquito which feeds on humans. "This theory is supported by the observation of Gabonese children displaying a higher risk of developing severe malaria when presenting with a high CNV of the FCGR2C gene." (PMID 33281811, 2020). "The association between CNV and severe malaria has also been reported for FCGR2C genes." (PMID 33281811, 2020). "Further studies are needed to elucidate the precise role of the FCGR2C gene in the response to malaria." (PMID 33281811, 2020).
NK/T-cell lymphoma (1 paper, 2021). "We identified four ENKTL markers (ZNF141, FCGR2C, NES and CDC27) in patients with extranodal NK/T-cell lymphoma." (PMID 34872521, 2021).
Obesity (1 paper, 2023). Accumulation of substantial excess body fat. "The hub genes calculated by Cytoscape software are MNDA (score 320), CYBB (score 314), CD86 (score 312), FCGR2C (score 242), NCF2 (score 240), LCP2 (score 182), TLR8 (score 148), HLA-DRA (score 54), LCP1 (score 30), and PTPN22 (score 8), which are considered to be associated with obesity-related AF." (PMID 36671813, 2023).
Sepsis (1 paper, 2022). Sepsis is defined as life-threatening organ dysfunction caused by a dysregulated host response to infection. "FCGR2C could be an immune biomarker associated with prognosis, which may be a new direction of immunotherapy to reduce sepsis mortality." (PMID 36532072, 2022). "The functional role of FCGR2C in sepsis requires more rigorous experiments to explore." (PMID 36532072, 2022). "Collectively, these findings suggest that FCGR2C is differentially expressed in sepsis." (PMID 36532072, 2022). "In conclusion, FCGR2C may be a novel immune marker related to sepsis prognosis." (PMID 36532072, 2022). "Interestingly, we first found that FCGR2C may be an emerging immune gene for predicting sepsis outcomes." (PMID 36532072, 2022). "Moreover, we found that FCGR2C may be a prognostic immune indicator in sepsis." (PMID 36532072, 2022).
tumor (4 papers, 2019 to 2023). "The Lgals9-based network by Cytoscape showed extensive and complex correlation between Lgals9 and other molecules in tumor-immune microenvironment, including CD4, CD19, CD79A, CIS, IL2RG, FCGR2C, and FASLG." (PMID 33082168, 2020).
cancer (3 papers, 2019 to 2021). A tumor composed of atypical neoplastic, often pleomorphic cells that invade other tissues. "For example, many studies investigating associations with therapeutic efficacy of therapeutic antibodies against cancer have found an association with the FCGR3A-158V variant (rs396991), which we now show to be in moderate LD with the classic FCGR2C-ORF (r2 = 0.24)." (PMID 30949161, 2019). "However, there is a need for further research to understand the function of FCGR2C and HAPLN3 in cancer." (PMID 33428606, 2021).
FCGR2C also shares sentences with these, for which no sentence is quoted: idiopathic thrombocytopenic purpura (2 papers); periodontitis (2); rheumatoid arthritis (2); systemic lupus erythematosus (2); asthma (1); atrial fibrillation (1); breast carcinoma (1); cardiovascular diseases (1); COVID-19 (1); Crohn disease (1); head and neck squamous cell carcinoma (1); infection (1); psoriasis (1); sickle cell disease (1); type 1 diabetes (1).